CRIP2 (cysteine rich protein 2)
Synonyms: CRP2; ESP1; CRIP
Tractability: Antibody: the Human Protein Atlas places it where antibodies can reach. PROTAC: ubiquitination databases record sites on it; its protein half-life has been measured.
Gene: Protein-coding gene on chromosome 14 (105,472,962 to 105,480,162, forward strand). Ensembl gene ENSG00000182809.
Subcellular location (Human Protein Atlas): Nucleoli; Nucleoplasm; Plasma membrane
Gene Ontology:
Molecular function: protein binding; zinc ion binding
Cellular component: cell cortex
Genetic constraint (gnomAD): Loss-of-function variants: 32 observed, 27.66 expected, observed/expected ratio (o/e) 1.16, 90% interval 0.87 to 1.55. The synonymous counts are far from expectation, so gnomAD's model fits this gene poorly and the ratio says little. Missense variants: 389 observed, 245.4 expected, observed/expected ratio (o/e) 1.59, 90% interval 1.46 to 1.72. Synonymous variants: 177 observed, 108.34 expected, observed/expected ratio (o/e) 1.63, 90% interval 1.45 to 1.85.
Homologues: Orthologues: chimpanzee CRIP2 (95% identical), macaque CRIP2 (95% identical), guinea pig CRIP2 (95% identical), pig CRIP2 (94% identical), mouse Crip2 (93% identical), rat Crip2 (93% identical), dog CRIP2 (88% identical), tropical clawed frog crip2 (80% identical), zebrafish crip2l (73% identical). Paralogues in human: CRIP3 (61% identical), ZFHX3 (29% identical), ZFHX4 (28% identical), CRIP1 (25% identical), LHX2 (25% identical), ZFHX2 (25% identical), LHX9 (25% identical), LHX8 (21% identical), LHX3 (20% identical), LHX6 (20% identical), LHX4 (19% identical), LHX5 (19% identical), and 8 more.
Diseases named in the same sentence as CRIP2 in open-access papers:
CRIP2 is named in the same sentence as 31 diseases in open-access papers, as found by Europe PMC text mining. Sharing a sentence is not in itself a finding about the gene and the disease. The quoted sentences say what the papers report.
breast carcinoma (8 papers, 2016 to 2023). "miR-449a was implicated functionally in breast cancer pathogenesis, suppressing Cysteine-Rich Protein 2 (CRIP2) and altering cell viability, migration, invasion, in vivo tumor growth, and angiogenesis, thereby driving malignant phenotypes in these aggressive tumors." (PMID 26934316, 2016). "CRIP2 is a transcription factor, which is an unfavorable prognostic factor for breast cancer as well as colorectal cancer." (PMID 35281077, 2022). "Hoffmann and colleagues have shown that hypoxia promotes mesenchymal invasion in breast cancer cells mediated through upregulation of cysteine-rich protein 2, a component of the actin cytoskeletal machinery involved in invadopodia formation." (PMID 31980706, 2020). "Another group identified CRIP2 to be significantly downregulated by aberrant expression of miR-449a in breast cancer." (PMID 29662084, 2018). "To examine the biological significance of CRIP2 in breast cancer progression, we first evaluated endogenous CRIP2 expression in breast cancer cell lines." (PMID 26934316, 2016). "In summary, our findings support the model wherein overexpression of miR-449a in breast cancer suppresses CRIP2 activity, leading in turn to increased tumor growth, migration, invasion, as well as angiogenic signaling." (PMID 26934316, 2016). "Thus, both in vitro and in vivo data support a tumor suppressive activity of CRIP2 in breast cancer models." (PMID 26934316, 2016). "In this study, we investigated the nuclear role of cysteine-rich protein 2 (CRP2), a two LIM domain-containing F-actin-binding protein that we previously identified as a cytoskeletal component of invadopodia, in breast cancer cells." (PMID 37266453, 2023). "Cysteine-rich protein 2 (CSRP2), as a novel target of HIF-1α, attributes to breast cancer cell invasion under hypoxic conditions by regulating the formation of invadopodium actin backbone." (PMID 32215176, 2020).
esophageal cancer (3 papers, 2016 to 2025). A primary or metastatic malignant neoplasm involving the esophagus. "Bioinformatics analysis showed that the low expression of CRIP2 was associated with a later tumor stage of esophageal cancer." (PMID 40118853, 2025). "Bioinformatics analysis showed that low expression of CRIP2 was associated with later tumor stage and poorer prognosis in esophageal cancer." (PMID 40118853, 2025). "Similarly, CRIP2 has shown great potential in the diagnosis and prediction of diseases such as esophageal cancer, non-small cell lung cancer, colon cancer, high-grade serous ovarian cancer, and acute lymphoblastic leukemia." (PMID 40118853, 2025).
esophageal squamous cell carcinoma (3 papers, 2016 to 2020). Esophageal squamous cell carcinoma (ESCC) is a type of esophageal carcinoma (EC) that can affect any part of the esophagus, but is usually located in the upper or middle third. "CRIP2 has been reported to be a tumor-suppressor; its down-regulation was observed in esophageal squamous cell carcinoma and re-expression induced cell death." (PMID 26934316, 2016). "Cysteine Rich Protein 2 (Cysteine Rich Protein 2) may promote apoptosis of esophageal squamous cell carcinoma cells." (PMID 33401247, 2020). "Additionally, CRIP2 has been shown to induce apoptosis in esophageal squamous cell carcinoma by activating caspase 3 and 9 proteins." (PMID 29662084, 2018).
colon cancer (2 papers, 2020 to 2025). "Bioinformatics analysis showed that CRIP2 was a biomarker related to the immune microenvironment and a risk gene for the survival of patients with colon cancer." (PMID 40118853, 2025). "IRG signature of AXIN2, CCL22, CLEC10A, CRIP2, RUNX3, and TRPM5 is a reliable prognostic predictor for colon cancer patients." (PMID 33401247, 2020).
colorectal cancer (2 papers, 2020 to 2022). A primary or metastatic malignant neoplasm that affects the colon or rectum. "Similarly, colorectal cancer patients with high expression of CRIP2, PRAM1, HSPB2 or CERCAM had poorer OS comparing with low expressed groups (logrank = 0.0073, 0.0053, 0.0036 and 0.0023, respectively)." (PMID 33125346, 2020).
melanoma (2 papers, 2022 to 2025). A malignant, usually aggressive tumor composed of atypical, neoplastic melanocytes. "SHAP value analysis ranked RPL35, KHDRBS3, ATP6V0D1, and CRIP2 as the most important contributors to melanoma classification." (PMID 40909289, 2025).
nasopharyngeal carcinoma (2 papers, 2016 to 2018). A carcinoma arising from the nasopharyngeal epithelium. "In nasopharyngeal carcinoma, loss of CRIP2 promotes tumorigenesis and angiogenesis by interacting with NF-κB/p65 and compromises NF-κB-mediated proangiogenic cytokine expression including IL6, IL8, and VEGF44." (PMID 29662084, 2018). "A previous study in nasopharyngeal carcinoma demonstrated that CRIP2 overexpression in cell lines transcriptionally and functionally down-regulated NF-κB–mediated proangiogenic proteins such as IL-6, IL-8 and VEGF." (PMID 26934316, 2016). "In particular, nasopharyngeal carcinoma cell lines and tumors have decreased CRIP2." (PMID 26934316, 2016).
prostate carcinoma (2 papers, 2016 to 2025). A carcinoma that arises from epithelial cells of the prostate gland. "ADAM19’s ability to increase secretion of CRIP-2 may represent another possible anti-tumourigenic mechanism for ADAM19 in prostate cancer." (PMID 26912236, 2016). "Using SMR software, thousands of Europeans with genomes as reference and eQTLGen data (EQTLgen‐CIS‐EQTLS) and prostate cancer GWAS data for gene colocalisation analysis, we showed the results of prognostic model‐related genes (BMP6 and CRIP2)." (PMID 39789383, 2025).
cutaneous squamous cell carcinoma (1 paper, 2018). "Here the authors show, using both cell lines and animal models, that in cutaneous squamous cell carcinoma HOXA9 acts as a tumor suppressor and inhibits glycolysis by associating with CRIP2 to repress HIF-1α binding to target genes." (PMID 29662084, 2018).
heart failure (1 paper, 2022). Inability of the heart to pump blood at an adequate rate to meet tissue metabolic requirements. "Although the mechanism underpinning lower Crip2 expression in heart failure may be multi-factorial, it may be explained by the pH-sensitivity of CRIP2 and may also indicate that pHn is the more direct trigger, compared to pHc." (PMID 35357563, 2022).
ischemic stroke (1 paper, 2026). A stroke disorder caused by obstruction of blood flow to the brain, due to thrombotic (local blood clot formation) or embolic (due to a blood clot or other material traveling from another site) event. "Nevertheless, further research is necessary to elucidate the molecular mechanisms underlying CRIP2 regulation and its impact on ischemic stroke." (PMID 41550246, 2026). "Our findings underscore the critical role of NICD1 in ischemic stroke pathology through its regulation of CRIP2." (PMID 41550246, 2026). "Moreover, it is imperative to ascertain the potential adverse effects and constraints of targeting CRIP2 for the treatment of ischemic stroke." (PMID 41550246, 2026).
Lymphadenopathy (1 paper, 2020). Enlargement (swelling) of a lymph node. "After correction for multiple testing through the Benjamini-Hochberg procedure, the correlation between CRIP2 and the presence of supradiaphragmatic lymphadenopathy remained significant (corrected p = 0.03)." (PMID 32253542, 2020).
multiple myeloma (1 paper, 2025). "CRIP2 is considered to be a mitophagy-related gene in multiple myeloma, which can be used to predict the survival rate of multiple myeloma, and high CRIP2 expression is usually associated with poor prognosis." (PMID 40118853, 2025).
non-small cell lung carcinoma (1 paper, 2025). A group of at least three distinct histological types of lung cancer, including non-small cell squamous cell carcinoma, adenocarcinoma, and large cell carcinoma. "CRIP2 expression is upregulated in radiation-resistant non-small cell lung cancer, which may be achieved by regulating cell apoptosis and cell cycle." (PMID 40118853, 2025).
peritoneal disease (1 paper, 2020). "The number of sites with peritoneal disease was correlated with increased levels of ALDH3A2 (p = 0.03, τ = 0.36) and CRIP2 (p = 0.01, τ = 0.378)." (PMID 32253542, 2020).
Stroke (1 paper, 2026). Sudden impairment of blood flow to a part of the brain due to occlusion or rupture of an artery to the brain. "To determine whether Crip2 expression was altered in an in vivo stroke model, we utilized a transient middle cerebral artery occlusion (tMCAO) mouse model." (PMID 41550246, 2026).
tumor (16 papers, 2010 to 2026). "Among the differentially regulated genes, Cysteine Rich Protein 2 (CRIP2), a gene associated with tumor suppressor function, has been found to be the most downregulated in taxane-resistant cells." (PMID 41997904, 2026). "Indeed, increased expression of CRIP2 is associated with impaired tumor angiogenesis." (PMID 32070401, 2020). "The ubiquitination and degradation induced by ATOX1 after transferring copper to CRIP2 can activate autophagy by increasing the reactive oxygen species (ROS) level in lung cancer cells and participating in tumor progression." (PMID 40118853, 2025). "MDA‐MB‐231 cells that underwent stable transfection with CRIP2 exhibited notable decreases in cell viability, migration and invasion, alongside diminished tumour growth and angiogenesis in mouse xenograft models." (PMID 39789383, 2025). "The presence of Crip2 has been observed in the endothelial cells of the neovasculature during the processes of wound healing and tumour growth." (PMID 39789383, 2025). "CRIP2 interacts with the NF-κB/p65 to inhibit its DNA-binding ability to the promoter regions of the major pro-angiogenesis cytokines critical for tumor progression, including VEGF." (PMID 32070401, 2020). "hsa-miR-449a targets cysteine-rich intestinal protein 2 (CRIP2) mRNA, a transcription factor and a tumor suppressor." (PMID 32070401, 2020). "CRIP2 expression significantly reduced tumor microvasculature density as well as decreased Ki-67 (a proliferative marker) expression." (PMID 26934316, 2016). "MiR-449a suppresses CRIP2 expression, which then leads to increased tumor formation (as well as migration and invasion), along with the activation of proangiogenic cytokines such as VEGF, possibly via the NF-κB/p65 complex." (PMID 26934316, 2016). "MDA-MB-231 cells stably transfected with CRIP2 demonstrated a significant reduction in cell viability, migration, and invasion, as well as decreased tumor growth and angiogenesis in mouse xenograft models." (PMID 26934316, 2016). "Our data revealed that overexpression of miR-449a suppresses CRIP2, which then affects the tumor vasculature, likely via NF-κB/p65 complex-mediated transcription of VEGF." (PMID 26934316, 2016). "Tumor involvement of the mesentery, which is a known important limiting factor in primary debulking surgery, was negatively correlated with the protein abundance of cysteine rich protein 2 (CRIP2)." (PMID 32253542, 2020). "CRIP2 regulates cell proliferation, and acts as a tumor suppressor." (PMID 32253542, 2020). "Moreover, we revealed the role of miR-449a in increasing tumor progression via CRIP2 repression, highlighting the potential importance of this new pathway in driving aggressive cancer behavior both in vitro and in vivo." (PMID 26934316, 2016). "Similarly, CRIP2 inhibits tumor progression and angiogenesis by inhibiting NF-κB-mediated transcription of pro-angiogenic cytokines IL-6, IL-8, and vascular endothelial growth factor, providing important evidence that CRIP2 acts as a tumor suppressor." (PMID 40118853, 2025). "Interestingly, CRIP2 is more likely to act as a tumor suppressor." (PMID 40118853, 2025). "Among them, the correlation between the CRIP2 protein and mesenteric diseases is strongest, and the abundance of other three proteins (STXVP2, ASS1, and CBD) is related to the heterogeneity of tumor location." (PMID 36091379, 2022). "Herein, CRIP2 was identified to be a direct interacting partner of HOXA9 and acted as a tumor suppressor in cSCC, consistent with the previous-reported anti-carcinogenic role of CRIP244,45,57." (PMID 29662084, 2018). "In contrast,EC5 and EC6 subclasses exhibited conserved pro-angiogenic signatures encompassing established vascular morphogenesis regulators (CD34,AQP1) and emerging angiocrine signaling components (RAMP2/3,CRIP2,PCDH17),consistent with previous reports on tumor neovascularization dynamics." (PMID 41394809, 2025). "CLEC10A and CRIP2 were negative in both normal and tumor tissues." (PMID 33401247, 2020).
cancer (11 papers, 2014 to 2025). A tumor composed of atypical neoplastic, often pleomorphic cells that invade other tissues. "Therefore, this study identified CRIP2 as an autophagy-inhibiting protein and linked CRIP2-mediated copper metabolism to autophagy in cancer cells." (PMID 37777761, 2023). "Cysteine-rich protein 2 (CSRP2) has been implicated in many types of cancer." (PMID 34585646, 2021). "Cancer cells accumulate copper, and studies have shown that CRIP2 can bind to the antioxidant 1 copper chaperone (ATOX1)." (PMID 40118853, 2025). "Cysteine-rich protein 2 (CSRP2) has been recently implicated in the progression and metastasis of a variety of cancers." (PMID 33042270, 2020). "Some of the identified factors (such as TSPAN8, CXCL17, CRIP2, STARD10, CSNK2A1) and pathways (i.e. apoptosis, TGFβ, VEGF and ERK signaling) are known to participate in cancer as well as their identification here linked with airway remodeling in mustard lung." (PMID 24978043, 2014). "The physiological roles of CRIP2 are not well described; however, reports have linked CRIP2 autophagy and glycolytic inhibition in the H1299 cancer cell line, alongside skeletal muscle and cardiovascular development." (PMID 39375833, 2024). "CRIP2 mediated copper metabolism activates autophagy in cancer cells." (PMID 35281077, 2022). "Here, via multiomics analyses of 314 SCLCs, we found that the ASCL1+/MKI67+ and ASCL1+/CRIP2+ clusters accounted for 74.38% of the 190,313 SCLC cancer cells from 39 patients, with the ASCL1+SOX1+ stem-like cell cluster across SCLC subtypes." (PMID 40925909, 2025).
cardiovascular diseases (1 paper, 2025). "In addition to its fundamental function in the cardiovascular system, CRIP2 is also involved in the pathological changes of cardiovascular diseases." (PMID 40118853, 2025).
CRIP2 also shares sentences with these, for which no sentence is quoted: abdominal aortic aneurysm (1 paper); adenocarcinoma (1); breast tumors (1); cardiomyopathy (1); hepatoblastoma (1); infection (1); lipoblastoma (1); lung carcinoma (1); neurodevelopmental disorder (1); pleomorphic adenomas of the salivary gland (1); psoriasis (1); squamous cell carcinoma (1).